INS (insulin)
Diseases named in the same sentence as INS in open-access papers (continued):
Sharing a sentence is not in itself a finding about the gene and the disease.
cancer (continued). "Other growth factor/hormone receptors that signal through the IRS proteins and that are associated with cancer include the insulin, prolactin, growth hormone (GH), and vascular endothelial growth factor (VEGF; KDR) receptors." (PMID 19534786, 2009). "Cancer can arise when mutations activate signaling downstream of insulin/IGF-I receptors leading to dysregulated cell growth." (PMID 16441841, 2006). "Wnt signaling pathways have been implicated in the pathogenesis of cancer, regulation of adipogenesis and insulin secretion." (PMID 16246260, 2005). "Future studies on cancer should examine comprehensively the inter-relationships among fasting insulin levels, insulin sensitivity, polymorphisms of the INS gene (either the VNTR or one of the surrogate SNPs), and risk of cancer." (PMID 12610512, 2003). "The insulin levels of the diabetics can be manipulated by medical intervention, rendering the genotype irrelevant for cancer risk." (PMID 12610512, 2003). "A comparison has been made between the effects of daily insulin injection and a ketogenic diet on weight loss and tumour weight in an experimental model of cancer cachexia (MAC16)." (PMID 2736199, 1989). "Finally, insulin itself is associated with increased cancer risk due to affinity for the Insulin-like growth factor (IGF-1) receptor." (PMID 41583363, 2026). "Notably, findings from the prospective, though uncontrolled, LABS study suggest that reductions in insulin, leptin, and ghrelin after bariatric surgery are independently associated with decreased cancer risk." (PMID 41490246, 2026). "Furthermore, the strongest association was seen for female-specific cancers among women with high baseline insulin levels, highlighting insulin status as a potential modifier of long-term cancer risk." (PMID 41490246, 2026). "The increased cancer risk observed in insulin-resistant individuals may also stem from ROS-mediated DNA damage, promoting mutagenesis and carcinogenesis." (PMID 41562933, 2026). "Future studies powered to evaluate individual antihyperglycemic medications and medications by cancer site are still needed to fully understand these associations, especially considering the recent rapid increases in non‐insulin glucose‐lowering medication use." (PMID 41287203, 2026). "The use of exogenous insulin may increase the risk of cancer‐related death due to its mitogenic properties." (PMID 41287203, 2026). "The same can be suggested for cancer cachexia; a recent study shows the leaky gut (often associated with cancer cachexia) mouse model leads to impaired systemic glucose metabolism and insulin tolerance in skeletal muscle which improved after soluble dietary fiber supplementation." (PMID 40572244, 2025). "FRT4H mainly influenced glycerophospholipid metabolism and choline metabolism in cancer, which may be associated with immune modulation, membrane remodeling, and insulin sensitivity." (PMID 40870712, 2025). "Besides Hippo signaling, 14 other pathways were also significantly enriched in both network and phosphoproteomics analyses, including cancer-associated pathways such as insulin signaling and cell cycle regulation." (PMID 41567641, 2025). "Others will experience amelioration of insulin needs with loss of appetite as they approach end‐of‐life, whether from malignancy, heart failure or whatever." (PMID 40035222, 2025). "Moreover, increased muscle mass improves metabolism and insulin sensitivity, as well as reduces adipose tissue deposition, a major risk factor for several cancers." (PMID 40396701, 2025). "Leptin regulates appetite and energy balance by influencing the hypothalamus, while adiponectin is responsible for enhancing insulin sensitivity and is known to have anti-inflammatory properties, with lower levels associated with obesity, diabetes, and increased cancer risk." (PMID 40551741, 2025). "Studies have identified insulin and insulin secretagogues as hypoglycemic agents that may increase cancer risk." (PMID 40429290, 2025).
cancer (continued). "Furthermore, future research should consider body composition alongside insulin resistance when evaluating cancer risk to better understand the potential contribution of metabolic dysfunction to cancer development and guide more precise preventive strategies." (PMID 41374929, 2025). "Our data support the notion that during the development of cancer cachexia, glycolytic skeletal muscles may become insulin resistant, causing metabolic dysregulation that can lead to eventual muscle weakness and wasting." (PMID 40985218, 2025). "These agents modulate insulin secretion, reduce systemic inflammation, and promote metabolic homeostasis, which may contribute to a lower cancer risk." (PMID 40364115, 2025). "Given that insulin has the ability to cause cancer, hyperinsulinemia may increase the bioactivity of insulin-like growth factor I (IGFI), improve growth factor-dependent cell proliferation, and/or have a direct impact on cellular metabolism." (PMID 40756600, 2025). "Therapeutic strategies, including hormonal interventions, insulin sensitizers, and lifestyle modifications, may mitigate cancer risk by modulating these pathways." (PMID 40534880, 2025). "Other strategies targeting insulin resistance support this rationale: metformin has shown antitumor effects in preclinical models and improved outcomes in diabetic cancer patients, whereas exogenous insulin use has been associated with a modestly increased risk of gastrointestinal tumors." (PMID 41178954, 2025). "Metformin therapy is an established treatment for T2DM patients who have elevated serum glucose and insulin levels which could promote cell proliferation and cancer risk." (PMID 40563926, 2025). "Because insulin is more likely to be used by patients with severe and long-term symptoms, this population may face a higher risk of cancer." (PMID 39774829, 2025). "Collectively, controlling blood glucose levels and improving insulin sensitivity may serve as effective strategies in reducing cancer risk and improving patient outcomes." (PMID 40387523, 2025). "TRIB3 is a stressor sensor involved in the alterations of the cellular microenvironment and various stress-inducing factors, including insulin, glucose deficiency, and the accumulation of misfolded proteins within the endoplasmic reticulum, and it has a tumorigenic role in different cancers." (PMID 39941896, 2025). "In addition, the overproduction of reactive oxygen species in insulin-resistant individuals increases the risk of cancer, causes DNA damage and mutagenesis, and causes carcinogenesis." (PMID 40756600, 2025). "Salt and additives in ultra-processed foods may influence several physiological processes associated with cancer development, including inflammation, insulin resistance and alteration of gut flora." (PMID 38999742, 2024). "A discussion on the insulin–cancer relationship includes four consecutive studies arguing that insulin, in particular insulin glargine, used for DM treatment, is associated with an increased risk of cancer." (PMID 39434861, 2024). "Furthermore, metformin helps in lowering the risk of cancer incidence in patients treated with SUs or insulin." (PMID 39410536, 2024). "However, elderly weight-losing cancer patients are usually insulin resistant related to loss of appetite and systemic inflammation." (PMID 39039509, 2024). "An increase in insulin concentration caused by IR may have mitogenic and anti-apoptotic effects and stimulate cell cycle progression in cancer cells." (PMID 38273418, 2024). "A comprehensive retrospective cohort study utilizing a nationwide electronic health records database of over 1.6 million diabetic patients revealed that GLP-1RAs were associated with significantly reduced risks for 10 out of 13 organ-associated cancers, when compared to insulin." (PMID 39595655, 2024).
cancer (continued). "The debate on whether the insulin analog glargine increases the risk of cancer in T2DM patients stems from four epidemiological articles published in Diabetologia in 2009." (PMID 39434861, 2024). "Of those cancers that showed a decreased risk among patients taking GLP-1RAs compared with those taking insulin, HRs for patients taking GLP-1RAs vs those taking metformin for colorectal and gallbladder cancer were less than 1, but the risk reduction was not statistically significant." (PMID 38967919, 2024). "Some evidence suggested that insulin glargine might pose a higher risk of cancer compared to human insulin." (PMID 38254789, 2024). "Moreover, future research should focus on elucidating the mechanisms by which insulin and glucose metabolism influence cancer development and exploring the efficacy of metabolic-targeting therapies in reducing cancer risk and improving patient outcomes." (PMID 39588310, 2024). "Insulin is proposed to be an oncogenic factor and is closely associated with cancer progression." (PMID 38392069, 2024). "Through a variety of mechanisms, such as altered sex hormone metabolic processes, increased adipokine synthesis, enhanced activation of insulin-dependent signaling pathways, and changes in the composition of the gut microbial community, adipose tissue increases the risk of cancer development." (PMID 39574952, 2024). "This has sparked increased interest in exploring the role of endogenous insulin in cancer risk." (PMID 38339407, 2024). "Additionally, a cohort study of more than 127,000 patients with DM from Germany showed a dose–response relationship between glargine use and cancer risk compared to human insulin users." (PMID 39434861, 2024). "Further research examined the cancer risks associated with different insulin secretagogues." (PMID 39595655, 2024). "The observed correlation between metabolic syndrome and elevated cancer risk may be attributed to heightened insulin levels, recognized as growth hormones, and implicated in the development of various cancer types, including PCa." (PMID 38672620, 2024). "Several scientific studies have established a significant association between body fat percentage and cancer risk, increasing insulin resistance, inflammation, and altering leptin levels, inducing changes in the metabolism, and causing an increase in the risk of up to 13 different types of tumors." (PMID 38338203, 2024). "While certain observational studies have hinted at a potential association between insulin usage and cancer susceptibility, these conclusions necessitate further refinement given the incomplete consideration of variables such as dosage, time span, and duration of insulin exposure." (PMID 38504335, 2024). "Moreover, continuous efforts to replace insulin with insulin analogs emphasize the significance of understanding the mechanisms of irregularities in insulin signaling and their potential impact on cancer mortality risk." (PMID 38272982, 2024). "The use of insulin is also associated with reduced cancer risk." (PMID 39076779, 2024). "Insulin levels are decreased in patients with cancer with severe malnutrition or weight loss." (PMID 38273418, 2024). "Consequently, it is crucial to improve our understanding of how insulin therapy affects cancer risk and progression." (PMID 39434861, 2024). "Severe malnutrition or weight loss in cancer patients accompanies decreased insulin levels." (PMID 38273418, 2024). "This is not a favorable effect, given that fat-free mass, particularly muscle mass, may produce a number of myokines with anti-inflammatory effects and increased insulin sensitivity, which is consequently associated with a reduced risk of cancer development." (PMID 38892682, 2024). "Several studies have suggested that insulin therapy could be associated with elevated cancer risk due to its mitogenic effects, potentially fostering the growth of certain cancer types." (PMID 39001440, 2024).
cancer (continued). "The high risk of cancer in insulin-resistant individuals may also be due to overproduction of reactive oxygen species (ROS)." (PMID 38904041, 2024). "In 2009, 4 independent studies suggested that exogenous insulin may be associated with an increased risk of cancer, although more recent epidemiological studies seem to refute this hypothesis." (PMID 38935200, 2024). "The dysregulation of insulin signaling pathways observed in MetS may contribute to the increased risk of these cancers, highlighting the potential importance of targeting IR in prevention and treatment strategies." (PMID 39731011, 2024). "Irregularities in insulin signaling have significantly increased the risk of various cancers, yet the precise underlying mechanisms remain unclear." (PMID 38272982, 2024). "Daily SCFA consumption (in moderation) through SCFA-rich food products may hold great potential to improve insulin sensitivity and provide substantial health benefits, including reducing the risk of cancer." (PMID 37290429, 2024). "We also discuss how diagnostic miRNAs have a significant role in reprogramming cancer metabolism, as we underline emerging evidence suggesting a crucial role of miRNAs in regulating metabolic processes such as insulin sensitivity, glucose and lipid metabolism, and energy homeostasis." (PMID 37637043, 2023). "DUET also promoted improvements in levels of CRP and glucose that have been observed in other more intensive weight loss interventions among cancer survivors, though few differences were detected in other biomarkers typically associated with weight loss, i.e., leptin, adiponectin, and insulin." (PMID 36900368, 2023). "This is crucial because type 1 diabetes is caused by autoimmune destruction of the islets and resulting insulin deficiency, whereas type 2 diabetes is linked to insulin resistance, inflammation, and high insulin levels, which drive the initiation and progression of cancers." (PMID 36533539, 2023). "Increased insulin levels may trigger the cancer associations of several additional risk factors, comprising high waist circumference, visceral fat, body mass index, sedentary lifestyle, and an inadequate food intake, among others." (PMID 36674935, 2023). "The potential mechanisms supporting the positive association between sugars and cancer, have already been discussed and include adiposity and insulin signaling pathway disruption, hormonal imbalances, inflammation, oxidative stress, DNA damage, and alteration of gene expression." (PMID 38024345, 2023). "The mechanisms underlying the role of excess body weight in advanced-stage cancer are thought to be due to higher levels of hormones and growth factors, such as insulin and leptin, and lower levels of testosterone, which may promote carcinogenesis." (PMID 38020965, 2023). "Moreover, when the risk of insulin requirement was evaluated by type of cancer, we detected a significantly increased adjusted HR for liver, gallbladder, pancreas, lung, and hematologic cancers." (PMID 36831436, 2023). "Alterations in insulin signal transduction increase the risk of cancer development." (PMID 36975518, 2023). "Moreover, in vitro and in vivo studies have demonstrated that insulin and IR are strongly associated with cancer progression." (PMID 37779149, 2023). "According to some previous population-based observational studies, insulin may be related to an increase in cancer risk owing to the increased expression of IGFR and the corresponding signaling pathway, leading to stimulation of cell proliferation." (PMID 36430639, 2022). "Albeit values of insulin sensitivity indices (ISIs), denoting IR, were associated with an increased risk for specific types of cancer, e.g., prostate and endometrial cancer, such an association with malignancy associated mortality is still not established, with contradicting results." (PMID 35921366, 2022).
cancer (continued). "We previously showed after a 29-year follow up of the GOH cohort, that individuals in the upper quartile of the fasting insulin had an increased risk, although with borderline statistical significance, for all-site cancer mortality (HR = 1.37, 95% CI: 0.94, 2.00, p = 0.097)." (PMID 35921366, 2022). "IR in patients with cancer is characterized by increased hepatic glucose production and gluconeogenesis, and unlike T2D, normal fasting glucose is associated with high, normal, or low levels of insulin." (PMID 35752767, 2022). "Sulfonylureas, as well as glinides and insulin, are associated with increased risk of cancer." (PMID 35158824, 2022). "SU has been suspected to increase cancer risk because it promotes insulin secretion." (PMID 36429732, 2022). "Hyperinsulinemia is related to cancer risk, whereas metformin is an insulin-sensitizing drug." (PMID 36430639, 2022). "The links between dietary carbohydrates and cancer risk are hypothesized to involve mechanisms that directly implicate players in insulin-mediated pathways across various tissues, as well as through the modulation of IGF-1 bioactivity." (PMID 35335158, 2022). "Furthermore, HepG2 cells demonstrate important characteristics of cancer cells, including loss of contact inhibition, aberrant glucose metabolism and an altered insulin signaling pathway machinery." (PMID 36009822, 2022). "Although less commonly studied, androgen deprivation therapy, radiotherapy, and stem cell transplant, as well as chemotherapy in combination with radiotherapy, also appear to pose an increased risk of excess weight and impaired insulin sensitivity in cancer survivors." (PMID 35244142, 2022). "Poor glycaemic control may be, in turn, a sign of underlying cancer and thus an association between cancer incidence and use of insulin in the short term could be due to reverse causality." (PMID 35681699, 2022). "Cancer-induced reprogramming of the host's glucose metabolism may cause insulin resistance and further decrease the serum albumin production." (PMID 36046647, 2022). "Moreover, the addition of metformin ameliorates the increased risk of cancer in patient therapy with sulfonylurea or insulin." (PMID 35222270, 2022). "Based on this, the tumorigenic effect of insulin is primarily driven by mutated cancer genes." (PMID 35252207, 2022). "Current research on the causes of obesity-mediated cancer progression focuses on soluble factors, such as increased circulating levels of insulin and other growth factors, altered inflammatory status, and the release of inflammatory molecules and fatty acids from dyslipidemia." (PMID 36291860, 2022). "A meta-analysis of all cancer deaths in non-diabetics reported that fasting serum insulin was associated with increased mortality (HR 1.92) in men and the French TELECOM study reported that elevated fasting insulin posed increased risk of cancer death (HR 2.30) in men over a 28-year follow-up." (PMID 35984550, 2022). "Metformin has been reported to decrease cancer risk or cancer mortality, whereas insulin and sulfonylureas might be associated with increased cancer risk." (PMID 36033393, 2022). "Indeed, exercise, by reducing visceral body fat, among other mechanisms, reduces chronic inflammatory syndrome, increases insulin sensitivity, especially in the muscles and liver, and ultimately reduces the risk of cancer." (PMID 36358820, 2022). "Some studies propose that higher levels of blood glucose and insulin are cancer risk factors." (PMID 35705722, 2022). "Increased circulating insulin and insulin-like growth factor levels also have been linked with cancer progression, suggesting that both obesity and insulin resistance might promote cancer development by activating cell growth signaling pathways." (PMID 35955833, 2022).